ART4 (ADP-ribosyltransferase 4 (inactive) (Dombrock blood group))
Synonyms: ARTC4; CD297; DO; DOK1; DO/ART4
Tractability: Antibody: its Gene Ontology location is reachable by antibodies, with high confidence; UniProt places it where antibodies can reach, with medium confidence; UniProt predicts a signal peptide or a membrane-spanning region. PROTAC: its protein half-life has been measured.
Gene: Protein-coding gene on chromosome 12 (14,825,569 to 14,843,526, reverse strand). Ensembl gene ENSG00000111339.
Subcellular location: Cell membrane
Subcellular location (Human Protein Atlas): Rods & Rings; Predicted to be secreted
Pathways (Reactome):
Metabolism of proteins: Post-translational modification: synthesis of GPI-anchored proteins
Gene Ontology:
Molecular function: NAD+ poly-ADP-ribosyltransferase activity; NAD+-protein-arginine ADP-ribosyltransferase activity
Biological process: arginine metabolic process
Cellular component: extracellular region; plasma membrane
Genetic constraint (gnomAD): Loss-of-function variants: 12 observed, 21.73 expected, observed/expected ratio (o/e) 0.55, 90% interval 0.35 to 0.89. The upper end of that interval is the gene's LOEUF score, 0.89, which puts it in group 3 of 6, group 1 being the genes least tolerant of losing a copy. Missense variants: 320 observed, 342.52 expected, observed/expected ratio (o/e) 0.93, 90% interval 0.85 to 1.02. Synonymous variants: 126 observed, 129.97 expected, observed/expected ratio (o/e) 0.97, 90% interval 0.84 to 1.12.
Homologues: Orthologues: chimpanzee ART4 (99% identical), macaque ART4 (92% identical), rabbit ART4 (74% identical), pig ART4 (69% identical), guinea pig ART4 (67% identical), dog ART4 (67% identical), mouse Art4 (59% identical), rat Art4 (59% identical), tropical clawed frog XB5918646 (29% identical), zebrafish si:ch211-145b13.6 (15% identical). Paralogues in human: ART1 (32% identical), ART5 (26% identical), ART3 (22% identical).
Diseases named in the same sentence as ART4 in open-access papers:
ART4 is named in the same sentence as 9 diseases in open-access papers, as found by Europe PMC text mining. Sharing a sentence is not in itself a finding about the gene and the disease. The quoted sentences say what the papers report.
sarcopenia (3 papers, 2022 to 2025). Progressive decline in muscle mass due to aging which results in decreased functional capacity of muscles. "They ultimately identified five candidate causal proteins associated with sarcopenia, including LILRB2, ASPN, CNTN2, ART4 and SOD2." (PMID 39949133, 2025). "We investigated the putatively potential causal effects of genetically predicted plasma protein levels on sarcopenia-related traits and identified three putatively causal proteins for ALM (LILRB2, ASPN, and CNTN2) and two for handgrip strength (ART4 and SOD2)." (PMID 35938019, 2022).
glioma (1 paper, 2012). A benign or malignant brain and spinal cord tumor that arises from glial cells (astrocytes, oligodendrocytes, ependymal cells). "Nine TAPPs from the glioma cells (Aim2, Art-4, EphA2, EZH2, Fosl1, PTH-rP, Sox11, Whsc2 and YKL-40) consistently exhibited increased mRNA presence (≥1.9-fold expression) after culturing the cells in hypoxia (1% O2)." (PMID 22957023, 2012). "Many of the TAPP were not differentially expressed in the hypoxic cells but nine TAPPs from the glioma cells (Aim2, Art-4, EphA2, EZH2, Fosl1, PTH-rP, Sox11, Whsc2 and YKL-40) consistently exhibited increased mRNA presence after culturing the cells in response to hypoxia." (PMID 22957023, 2012). "Hypoxic glioma cell lines increased their mRNA expression for nine TAPP (Aim2, Art-4, EphA2, EZH2, Fosl1, PTH-rP, Sox 11, Whsc2 and YKL-40), as assessed by quantitative reverse transcriptase real-time/polymerase chain reaction (qRT-PCR)." (PMID 22957023, 2012).
malaria (1 paper, 2021). Malaria is a serious and sometimes fatal disease caused by a parasite that commonly infects a certain type of mosquito which feeds on humans. "We showed that ART4 and AQP1 polymorphisms exhibit significant associations with severe malaria and parasite density and that protective allele in both loci occur with higher frequency in populations of African descent compared to those of European descent." (PMID 34880413, 2021). "We also found that genetic variants in both ART4 and AQP1 are associated with susceptibility to the disease in a malaria-endemic population." (PMID 34880413, 2021). "Moreover, genetic variations at both the ART4 and AQP1 loci are significantly associated with severe malaria and parasite density in children from a Sub-Saharan African malaria-endemic country." (PMID 34880413, 2021).
cancer (4 papers, 2002 to 2023). A tumor composed of atypical neoplastic, often pleomorphic cells that invade other tissues. "In regard with SART-1, -2, -3, and ART4 antigens, we previously reported their protein expression in many samples of the majority of epithelial cancer cells and tissues by Western blot and Northern analyses." (PMID 12232766, 2002). "ART4 is an ADP-ribosyltransferase and can modulate the evasion of growth suppressors, cell death resistance and genome instability in cancer." (PMID 38003247, 2023).
adenocarcinoma (1 paper, 2023). A common cancer characterized by the presence of malignant glandular cells. "In both the adenocarcinoma and SCC groups, there were no statistically significant changes in heart V20, V30, and Dmean values when comparing ART1 to ART4." (PMID 37761323, 2023).
infection (1 paper, 2021). The state of being infected such as from the introduction of a foreign agent such as serum, vaccine, antigenic substance or organism. "We showed that ART4 and AQP1 coalesce in proximity to the parasite entry site upon invasion, suggesting an infection-dependent remodeling of erythrocyte membrane microdomains." (PMID 34880413, 2021).
ART4 also shares sentences with these, for which no sentence is quoted: cervical cancer (1 paper); infectious disease (1); viral infection (1).